BCL2 (BCL2 apoptosis regulator)
Diseases named in the same sentence as BCL2 in open-access papers (continued):
Sharing a sentence is not in itself a finding about the gene and the disease.
tumor (continued). "Obatoclax, a BCL-2 inhibitor, demonstrated significant inhibition of colorectal liver metastases in a CT26 tumor model." (PMID 38555418, 2024). "The majority of cases are also positive for BCL2 and CD99, and less than half the neoplasms show expression of smooth muscle actin (SMA) and S100." (PMID 39062853, 2024). "Differentially abundant proteins between tumor and healthy samples included PI3K, MAPK, BCL2, and PPIA proteins, which are involved in various biological pathways related to cell proliferation and growth." (PMID 39409902, 2024). "Glabridin promotes tumor cell apoptosis by upregulating BAX, Caspase-3, Caspase-8, and Caspase-9 and downregulating Bcl-2, and inhibits cancer cell invasion and metastasis by downregulating N-Cadherin and upregulating E-Cadherin to reduce cell adhesion." (PMID 39723390, 2024). "In the FBP1 knockdown group, the levels of the anti‐apoptotic protein bcl‐2 markedly decreased while that of bax increased in A549 and NCI‐H1975 cells, demonstrating that FBP1 plays a tumour‐suppressive role in LC." (PMID 38693853, 2024). "Up to now, immunohistochemical staining has usually shown that tumor cells differentially express CD34, BCL-2, wave proteins and CD99, which are almost always positively or strongly positively expressed in SFT." (PMID 39015488, 2024). "Several targets showed specifically higher expression in HET cases, including TIM3, BCL2, S100B, and CD44 (tumor ROI only), implying a more immunosuppressive microenvironment within these tumors." (PMID 38300710, 2024). "NFκB facilitates tumor cell survival, proliferation, and angiogenesis by regulating the expression of target genes such as cyclin D1, IL6, BCLXL, BCL2, XIAP, and VEGF." (PMID 39203892, 2024). "Recently, it was reported that the BCL2 inhibitor venetoclax, a BCL2 homology 3 (BH3) mimetic, can induce apoptosis by lowering the apoptosis threshold of tumor cells." (PMID 39086951, 2024). "Continuous exposure of tumor cells to drugs increases the expression of proteins such as Bcl-2, IAP, and Akt, which inhibit apoptosis and accelerate tumor proliferation, or proteins like P-gp, which transport intracellular drugs out of the cells." (PMID 39274842, 2024). "Overexpressed pro-survival B-cell lymphoma-2 (BCL-2) family proteins BCL-2 and BCL-XL can render tumor cells malignant." (PMID 38368459, 2024). "Our scRNA-seq and ST analyses revealed that BCL2 (BCL-2) and BCL2L2 (BCL-w) are expressed at low levels in tumor cells and have low tumor specificity." (PMID 39122703, 2024). "Therefore, the APG-2575-induced enhancement of the effects of anti-PD-1 therapy might not be associated with tumor BCL-2 inhibition." (PMID 38062129, 2024). "Typical findings associated with stromal sarcoma involve positive expression of vimentin, cytokeratin, CK7, CD99, Bcl-2, SS18-SSX2, and SYT-SSX in the tumor cells." (PMID 39079400, 2024). "Some data indicate the involvement of neuropeptides in the survival of tumor cells by activating the MAPK/ERK pathway and autocrine/paracrine stimulation of Bcl-2 expression." (PMID 38674047, 2024). "The immature T-cell tumor, with high Bcl-2 expression, showed significantly greater sensitivity to ABT-199 compared to the mature tumor." (PMID 39684550, 2024). "STAT3 plays a critical role in the development of apoptosis abnormality in tumor cell lines, which promotes an apoptosis-resistant environment via the activation of survivin, NFAF and Bcl-2." (PMID 38733520, 2024). "The findings revealed that treatment with hemagglutinine resulted in downregulation of CD34, Ki67, EGFR, Bcl-2, and VEGF expressions in tumor tissues while up-regulating the pro-apoptotic protein Bax expression." (PMID 38751791, 2024). "The tumor cells had intense cytoplasmic CD45, membrane-cytoplasmic CD3, cytoplasmic Bcl-2, CD8, and membrane CD56 expression." (PMID 39583401, 2024).
tumor (continued). "In vivo, 5 mg/kg weekly dosing of 753b was found to lead to significant tumor growth delay, similar to the DT2216 + venetoclax combination in H146 xenografts, by degrading both BCL-xL and BCL-2." (PMID 38534371, 2024). "Additionally, the differences in Bcl-2 expression patterns observed with Bcl-2 antibodies could be explained by selective caspase activation that leads to proteolytic degradation of Bcl-2 in tumor cells." (PMID 39252711, 2024). "Thus, inhibiting anti-apoptotic BCL-2 function may have a multi-pronged anti-tumour action." (PMID 38549077, 2024). "In endometrial cancer, adiponectin activates AMPK and downregulates Bcl-2 and MMP-9 expression, consequently inhibiting the invasion of tumor cells and promoting tumor cell apoptosis." (PMID 38800384, 2024). "STAT1/ STAT2 has a large number of target genes, including NO, BCL-2, p21, and CCND1, which all participate in pro-apoptotic and cell-cycle regulation, and act as tumor suppressors in various cancers." (PMID 38191598, 2024). "Their research revealed that UCA1 upregulates several tumour‐promoting genes such as CAMP responsive element‐binding protein 1 (CREB1), B‐cell lymphoma 2 (BCL2) and Ras‐related protein Rab‐22A (RAB22A) by sponging miR‐204‐5p, which is a tumour suppressor." (PMID 38506091, 2024). "Ginsenoside Rh2 inhibited tumor growth in TNBC mice and reduced the expression of IL- 6, IL-6R, STAT3, Bcl-2, and Bcl-xL in tumor tissues." (PMID 39845783, 2024). "As proposed as a tumor suppressor, miR-136-5p functionally interacts with a variety of target genes, such as ROCK1 41, BCL2 42, or SMAD3 43, to interfere with cancer cell invasion and migration." (PMID 38495489, 2024). "In the present study, western blotting demonstrated an increase in the ratio of Bax to Bcl-2, which indicates that DTP-PDT induces tumor cell death via the intrinsic apoptotic pathway." (PMID 38686054, 2024). "Specifically, we enhanced the NCCN‐IPI with combinations of stromal FOXC1 and tumor pERK1‐2 as well as cell of origin, MYC/BCL2 double expression, and tumor pERK1‐2." (PMID 39404228, 2024). "On immunohistochemistry, the tumor cells were diffusely and strongly positive for STAT6, BCL2, and CD34." (PMID 39021462, 2024). "CD133 correlated with levels of AKT serine/threonine kinase (AKT) and BCL2 apoptosis regulator (BCL2), and increased tumor propagation potential, corresponding with its role in cell stemness." (PMID 39456533, 2024). "On the other hand, it can down-regulate the expression of Bcl-2 and CDK-2, thus inhibiting the proliferation of tumor cells." (PMID 39057425, 2024). "The expression of BCL-2 and IκBα in the anti-JAM-A group were decreased in mice tumor tissues compared to the control group." (PMID 38495763, 2024). "Clinical observations demonstrated that the addition of Bcl2 inhibitors, such as Venetoclax, to standard therapy results in a rapid reduction in WBC counts, thereby reducing tumor burden and providing prompt symptom relief." (PMID 38939329, 2024). "Transcriptional factor TFAP2A controlled the expression of various tumor-related genes including VEGF, BCL-2, c-Kit and c-Myc, and was reported to be widely upregulated in tumor samples." (PMID 37064095, 2023). "Studies have demonstrated that PCP can suppress tumor cell growth by regulating Bcl-2/Bax protein, and carboxymethyl sulfated PCP can induce necrosis and apoptosis in tumor cells." (PMID 36903383, 2023). "Significant changes have been detected in the tumor microenvironment pathway including genes MMP19, MMP24, and CSF2, as well as PLAU, BCL2, TIAM1 and Rac1." (PMID 38003292, 2023).
tumor (continued). "AHCY-deficient SW480 cells exhibit significant upregulation of genes important for the tumor microenvironment pathway, such as MMP19, MMP24, and CSF2, as well as upregulated activation of PLAU and BCL2." (PMID 38003292, 2023). "The tumor stained positive for pancytokeratin, AE1/AE3, epithelial membrane antigen (EMA), TLE-1, CD99, and BCL-2." (PMID 38188535, 2023). "We identified that Bcl-2 and PARP1 protein expression was significantly downregulated in the CEP-inhibited tumor growth model, whereas Bax, Bad, cleaved caspase-3, and -9 protein expression was significantly upregulated." (PMID 38086844, 2023). "Opposite to these findings, in posterior uveal melanoma, miR-182 has been found to function as a suppressor tumor that suppresses the expression of MITF, Bcl-2, and cyclin D2." (PMID 37438760, 2023). "The expression of pro-apoptotic markers (CASP and BAX) and anti-apoptotic proteins (BCL-2 and BCL-XL) is used as an indicator of apoptosis induction in tumor cells." (PMID 37188770, 2023). "In terms of inhibiting tumor apoptosis, insulin resistance can lead to 5-FU resistance in HCC through activation of the PERK pathway and upregulation of Bcl-2 anti-apoptotic protein." (PMID 37790807, 2023). "Tissue immunofluorescence assay also confirmed that TRAF6 was correlated with the expressions of PKM2 and Bcl‐2 in chemoresistant TNBC patients, which shared the same location in TNBC tumor tissues." (PMID 37746908, 2023). "In conclusion, irisin has an apoptotic effect on PC-3, possibly through altering αVβ5 and the Bcl2/BAX and P13k-Akt signaling pathway, inhibiting tumor growth in vivo." (PMID 37568817, 2023). "Specific ASOs targeting eIF4E can inhibit tumor growth by suppressing the translation of target mRNAs such as VEGF, Survivin, C-Myc, Cyclin D1, and BCL-2." (PMID 37631029, 2023). "The NPs loaded with DOX and Bcl-2-targeting siRNA showed tumor accumulation in HepG2/adriamycin (ADM) tumor-bearing mice, resulting in reduced tumor growth and increased survival compared to controls." (PMID 37275244, 2023). "Western blotting results confirmed that vortioxetine hydrobromide reduced the levels of p-STAT3 Y705, c-Myc, Bcl-2 and Mcl-1 in PDX tumor xenografts." (PMID 37147297, 2023). "However, BCL2 may function as an oncogene or as a tumor suppressor gene in various types of cancer." (PMID 38003498, 2023). "This miRNA acts as a tumor suppressor gene by targeting DNMT3B, Bcl-2, PI3KR1, and AKT2, which radiosensitize the tumor by regulating DNA damage." (PMID 37958993, 2023). "In tumor-bearing mice, the EXO-RIF treatment group showed decreased Ki67 expression, elevated c-caspase-3 and Bax, and low Bcl-2 expression compared to RIF treatment." (PMID 37670948, 2023). "Conversely, in some tumor models, cells express low levels of BCL2 but are still highly sensitive to BCL-2 inhibition, indicating that the BCL2 protein is a small part of a more intricate process." (PMID 38263980, 2023). "For instance, EBV activates oncogenes such as Bcl-2 and MYC and deactivates tumor suppression genes." (PMID 36826111, 2023). "The obtained mouse tumor cells were subjected to RT-qPCR to examine the expressions of CYP4A22-AS1, EREG, and BCL-2." (PMID 37670265, 2023). "IHC analysis of patients showed that b-lymphocyte membrane markers (CD20 and CD79a), Bcl-2, Bcl-6 and MUM-1 were all positive in tumor cells." (PMID 36701728, 2023).
tumor (continued). "This increases the amount of Bcl-2, XIAP, and CDKs thus suppressing tumor development and inducing cell death." (PMID 37838685, 2023). "Once delivered to the tumor site, PDT with SLN-AlPc treatment yielded ROS generation, increased the expression of caspase-3, and decreased the expression of Bcl-2." (PMID 37622997, 2023). "Overexpression of miR-140-3p in vivo inhibited tumor growth in a LoVo xenograft model and diminished metastatic nodules in nude mouse liver and suppressed CRC progression by targeting BCL9 and BCL2." (PMID 37237523, 2023). "For instance, miR-21 is an oncogenic miRNA that targets tumor suppressor genes such as PTEN and PDCD4, while miR-34a is a tumor suppressor miRNA that targets oncogenes such as MYC and BCL2." (PMID 37460924, 2023). "Out of 21 ICD-related genes with notably different expressions, seven genes, namely ROCK1, BCL2, TLR2, TLR9, AGER, CASR, and P2RX7, were found to have decreased expression in tumor samples, while the rest were upregulated." (PMID 37932362, 2023). "mmunohistochemical staining showed that the tumor cells were positive for CD20, CD79a, PAX-5, Bcl6, MUM-1, CD19, c-Myc (Y69) (40%), and Bcl2 (80%)." (PMID 37884941, 2023). "Western blotting showed the elevated expression of E-cadherin and Bax, while CD276, Bcl-2, and JAK3-STAT3-Slug-pathway-related genes showed decreased expression, leading to repressed tumor growth in mice." (PMID 37237523, 2023). "We found in this study that the protein level of Bcl-2 decreased and that of Bax and cleaved caspase-3 increased, indicating that PROK1 silencing promoted the apoptotic death of tumor cells transplanted in nude mice." (PMID 37070074, 2023). "BCL-2 inhibitors can inhibit the binding of BCL-2 and BAX proteins to form a dimer so that the tumor cells can re-establish their normal apoptosis capacity." (PMID 37298069, 2023). "In vivo, brucine inhibited subcutaneous tumor formation in nude mice, and the expression of Ki67, COX-2 and Bcl-2 decreased while the expression of Casp3 and Bax increased in tumor tissues from nude mice with brucine treatment." (PMID 37779869, 2023). "In summary, these findings suggest that CYP4A22-AS1 exhibit tumor-promoting effects through down-regulated miR-205-5p and miR-34c-5p targeting EREG and BCL-2 in vitro and in vivo." (PMID 37670265, 2023). "Then, tumor growth rate, tumor necrotic area, the expression of the apoptosis-related genes CASP8, BCL-2, and BAX and the level of CASP8 protein were analyzed." (PMID 36661524, 2023). "BCL-2 has an oncogenic role because its overexpression increases AKT activity, which in turn plays a central role in inhibiting apoptosis in a variety of tumor types." (PMID 37189618, 2023). "There were more apoptotic cells in QRHXF group's tumor tissues, and QRHXF treatment increased BAX and cleaved-caspased 3 levels but decreased Bcl-2 levels." (PMID 36860928, 2023). "There are a number of tumor‐promoting factors in tumor cells such as IL‐17RB, IGF‐1R, MDR1, Bcl‐2, and HMGA2, among others, that can mediate resistance of cancer cells to DOX chemotherapy." (PMID 36684100, 2023). "This was thought to be mediated through the suppression of STAT3 signaling pathway and its downstream genes BCL2, c-MYC, and Survivin, which affect tumor growth by inducing apoptosis." (PMID 37189618, 2023). "A combination of Bcl-2 and YAP inhibitors demonstrated a synergistic effect, substantially reducing tumor area and invasiveness in Nf2-KO S1M cells, emphasizing the potential therapeutic value of this combination in NF2 deficient GC." (PMID 37730636, 2023).
tumor (continued). "As expected, our gene expression results demonstrated that the triple-drug combination (TME) significantly reduced the levels of BCL2 and enhanced the expression levels of BAX, BAD, caspase-9, 8 and 3 when compared to that of tumor-control group (p < 0.0001)." (PMID 37025487, 2023). "Drug-induced apoptosis, accomplished by the nitric oxide (NO) sensitization of tumor cells, resulted from inhibition of YY1 and its anti-apoptotic gene products Bcl-2 and Bcl-xL." (PMID 37686541, 2023). "PROCA1 played a potential tumor-suppressive role inducing cell apoptosis and DDP chemosensitivity via recruiting ZFP36L2 to bind to the 3′ untranslated region of BCL2, reducing the stability of BCL2 mRNA and thus activating the apoptotic signal." (PMID 36627670, 2023). "Similarly, flow cytometry experiments showed that HSN might cause apoptosis and G0/G1 phase arrest in Jurkat cells by lowering the Bcl-2 expression and, at the same time, enhancing Bax, mRNA, caspase-3, and -9 levels, thus inducing inhibition of cell proliferation in a tumor." (PMID 37630393, 2023). "Immunohistochemical staining revealed that the tumor cells were positive for CD34, CD99, Bcl-2, and STAT6." (PMID 37491539, 2023). "As a B-cell lymphoma-2 (Bcl-2) anti-apoptotic protein inhibitor, ABT737 has been shown to have potent anti-tumor effects against several types of tumors, including HCC." (PMID 38139458, 2023). "Immunohistochemistry results showed positivity for TLE1, EMA, BCL-2, CKH, CK18, and Kiel-67 (in 46% of cells) in some regions of tumor cells; and negativity for Desmin, CD34, S-100, and CD117 in tumor cells." (PMID 38013382, 2023). "PTHrP ablation leads to a significant decrease in tumor growth and metastasis as well as the reduced expression of several factors known to support tumor progression, including: CXCR4, Ki67, Bcl-2, AKT1, and Cyclin D1." (PMID 38435029, 2023). "According to miRDB: the microRNA database, miR-181a-5p has 887 target genes, including BCL2, LMO3, PTEN, SNAI2, WIF1, which are related to tumor development, cell cycle control, signal transduction processes, and apoptosis." (PMID 37697308, 2023). "Previously, we showed an anti-tumor effect of miR-195 in HNSCC via the inhibition of Cyclin D1 and BCL-2 expression." (PMID 38136338, 2023). "The upregulation of pro-apoptotic genes and downregulation of anti-apoptotic genes, mainly MCL1, PDK1 and BCL2, after MET and MET + LPS treatments contributed to the tumor cell death observed." (PMID 36765551, 2023). "While the BCL-2 inhibitor navitoclax successfully reduced metastases in mice with tumors, the MCL-1 inhibitor S63845 completely eradicated both senescent tumor cells and metastases." (PMID 37601693, 2023). "To date, the main recognized poor-prognosis genetic subtypes display tumour MYC and BCL2 translocations (‘double-hit lymphoma’) or MYC, BCL2 and BCL6 translocations (‘triple-hit lymphoma)." (PMID 37345090, 2023). "We further tested canonical apoptosis inducers BH3-mimetics such as navitoclax and venetoclax (BCL-2 inhibitors), as well as S63845 (MCL-1 inhibitor) and found both robust nuclear bursting and calcium spike in 4T1 tumor cells." (PMID 36973439, 2023). "Station 4 and 10 lymph nodes exhibited similar tumor cells and were immunohistochemically positive for CD10 and BCL2." (PMID 37012000, 2023). "Specifically, expression levels of BCL2, SLC40A1, and TFF1 were decreased in BCa samples with respect to normal tissues, whereas APOOL and PRAME were increased in tumor samples." (PMID 37728703, 2023).